CPT1A (carnitine palmitoyltransferase 1A)
Diseases named in the same sentence as CPT1A in open-access papers (continued):
Sharing a sentence is not in itself a finding about the gene and the disease.
Alzheimer disease (5 papers, 2020 to 2026). A progressive, neurodegenerative disease characterized by loss of function and death of nerve cells in several areas of the brain leading to loss of cognitive function such as memory and language. "Seven out of 18 genes are associated with neurological diseases: Alzheimer’s disease (CPT1A, SUFU, ZSWIM8, PDCD4), schizophrenia (HTT, NBEAL2) and Parkinson disease (PRDM13)." (PMID 32599769, 2020). "Interestingly, there were seven genes associated with neurological disorders, including Alzheimer’s disease (CPT1A, SUFU, ZSWIM8, PDCD4), schizophrenia (HTT, NBEAL2) and Parkinson’s disease (PRDM13)." (PMID 32599769, 2020). "We did not detect an association of CPT1A methylation levels with risk of all-cause or Alzheimer’s Dementia in FHS which could be due to a lack of power given the lower number of AD cases in FHS (4%) compared to ROSMAP (42%)." (PMID 37891690, 2023).
glioma (5 papers, 2018 to 2022). A benign or malignant brain and spinal cord tumor that arises from glial cells (astrocytes, oligodendrocytes, ependymal cells). "As such, researchers have considered etomoxir as a CPT-1a inhibitor, as it slows the proliferation of glioma cells and prolongs the patient’s time of survival." (PMID 36291824, 2022). "Moreover, FASN expression was relatively higher than CPT1a in all studied glioma cells which can be in correlation to the growing cell culture characteristics and metabolic shifts towards anabolic pathways." (PMID 30574020, 2018). "IHC analysis revealed that the three essential FAO enzymes CPT1A, CPT2, and ACAD9 were increased 86.96, 84.78, and 76.09% respectively in the recurrent gliomas, companied with 82.6% CD47 enhancement." (PMID 35314680, 2022). "The metabolomic data relating to the use of etomoxir to inhibit CPT-1a shows a reduction in NADPH levels and the induction of oxidative stress in the targeted glioma cells." (PMID 36291824, 2022). "Finally, our data suggest that the detected metabolic heterogeneity (the high mTORC2 complex activity, enhanced expression of Rictor, p-Akt, p-S6, CPT1A and LDHA enzymes in glioma cases) is a very promising combination target." (PMID 31187466, 2020). "In addition, several substrate utilisation capacities can be observed in these glioma cells (e.g. GLS and CPT1A protein expression levels are higher in glioma cells)." (PMID 31187466, 2020). "Finally, our data suggest that the detected metabolic heterogeneity (the high mTORC2 complex activity, enhanced expression of Rictor, p-Akt, p-S6, CPT1A, and LDHA enzymes in glioma cases) and the microenvironmental or treatment induced metabolic shift can be potential targets in combination therapy." (PMID 31187466, 2020). "In addition, temozolomide decreased lipid synthesis related FASN without influencing CPT1a expression in the studied glioma cells." (PMID 30574020, 2018).
heart failure (5 papers, 2016 to 2023). Inability of the heart to pump blood at an adequate rate to meet tissue metabolic requirements. "The clinical study of the CPT1A inhibitor etomoxir showed improvement in heart failure, but was ended prematurely due to elevated liver transaminase in enrolled patients." (PMID 37033619, 2023). "Genes related to FAO pathways, including CPT1A, were significantly low in expression in the patient (iTAZ) cardiomyocytes, while cardiac failure markers such as NPPA, NPPB, NKX2‐5 were upregulated in the same." (PMID 37533404, 2023). "The expressions of ACADM, FABP3, ECH1, ACAA2, EHHADH and CPT1A in the left atria were significantly up-regulated in the MR patients with heart failure compared to patients with aortic valve disease and heart failure and normal controls." (PMID 27250500, 2016).
atherosclerosis (4 papers, 2020 to 2024). A disease characterized by the build-up of fatty material and calcium deposition in the arterial wall resulting in partial or complete occlusion of the arterial lumen. "Our results are in agreement with previous reports in the field of atherosclerosis, showing that enforcing CPT1a expression can reduce, arguing that the induction of FAO in foam cells could be of therapeutic potential." (PMID 33002063, 2020). "This review focuses on the role and mechanism of action of miR-26 in atherosclerosis, including the detection value of miR-26 and the potential development of drugs targeting its downstream genes, such as ACC1/2, COL1A1, CPT1A, FBP1, DGAT2, and SMAD7, to provide insight for drug development." (PMID 38195542, 2024).
Burkitt lymphoma (4 papers, 2013 to 2022). A rare form of malignant mature B-cell non-Hodgkin lymphoma. "Targeting CPT1A has shown positive results for impairing cancer cell survival and inhibiting tumor cell proliferation in vitro and in vivo models of Burkitt’s lymphoma." (PMID 35411000, 2022).
cardiac hypertrophy (4 papers, 2021 to 2025). "For example, overexpression of MIAT exacerbates cardiac hypertrophy via the PPARα/CPT-1a signaling pathway." (PMID 40290189, 2025). "Carnitine palmitoyl transferase-1a (CPT-1a) is a key enzyme in mitochondrial fatty acid oxidation and has been reported in cardiac hypertrophy via PPAR/CPT-1a signaling pathway." (PMID 35383152, 2022). "Osthol could reduce rat cardiac hypertrophy by increasing PPARα mediated CPT-1a mRNA while decreasing DGAT mRNA." (PMID 35383152, 2022). "In this study, we demonstrated that MIAT influenced AngII-induced cardiac hypertrophy by regulating the expression of a key m6A RNA methylation enzyme, Ythdf2, and may influence its downstream target genes PPARα/CPT-1a." (PMID 35383152, 2022). "To explore the mechanism of Ythdf2 in cardiac hypertrophy, we investigated whether Ythdf2 and CPT-1a actually interacted, which may affect the cardiac hypertrophy in H9c2 cells." (PMID 35383152, 2022). "Finally, we found that MIAT was a necessary regulator of cardiac hypertrophy due to its regulation of the Ythdf2/PPARα/CPT-1a axis." (PMID 35383152, 2022). "In western blot analysis and RT-qPCR assays, the cells transfected with MIAT plasmid had increased mRNA and protein expression of cardiac hypertrophy markers ANP, BNP, and β-MHC, whereas PPARα and CPT-1a were notably decreased relative to mock or scramble groups." (PMID 35383152, 2022). "Similarly, knockdown of MIAT decreased cardiac hypertrophy markers ANP, BNP, and β-MHC, whereas PPARα and CPT-1a mRNA and protein levels were increased." (PMID 35383152, 2022). "Furthermore, the cells transfected with Ythdf2 plasmid had increased mRNA and protein expression of cardiac hypertrophy markers ANP, BNP, and β-MHC, whereas PPARα and CPT-1a were significantly decreased relative to control groups." (PMID 35383152, 2022). "Similarly, knockdown of Ythdf2 decreased cardiac hypertrophy markers ANP, BNP, and β-MHC, whereas PPARα and CPT-1a mRNA and protein levels were increased." (PMID 35383152, 2022).
hypertriglyceridemia (4 papers, 2016 to 2023). A laboratory test result indicating elevated triglyceride concentration in the blood. "In animal models, the expression level of CPT1A was associated with increasing BMI, WC, and hypertriglyceridemia." (PMID 36522620, 2022). "Thus increase the expression of CPT1A causes hypertriglyceridemia." (PMID 35551677, 2022). "DNA methylation mechanisms are reversible and new therapeutic approaches for treatment of hypertriglyceridemia can be used through modulating CPT1A expression." (PMID 35551677, 2022).
kidney damage (4 papers, 2023 to 2025). "Reduced levels of CPT1A protein have been associated with kidney damage in AKI and CKD patients and experimental models." (PMID 40076489, 2025). "In addition, CPT1A deficiency is associated with fibrosis in other models of kidney damage, suggesting that the alteration of enzymes involved in β-oxidation contributes to CKD development." (PMID 40227243, 2025). "In order to determine the critical role of β-catenin in modulating fatty acid metabolism, we examined the expression of CPT1A and PPARα, markers for fatty acid metabolism, in various clinical nephropathies." (PMID 39438470, 2024). "This supports that under kidney damage, overexpression of Cpt1a promotes a recovery of the physiological metabolic phenotype." (PMID 37377862, 2023).
lipid metabolism disorders (4 papers, 2023 to 2026). "Mechanistically, loss of Mettl3 significantly downregulated the expression levels of multiple m6A-modified mRNAs related to lipid metabolism, including Adh7, Cpt1a, and Cyp7a1, further promoting lipid metabolism disorders and liver injury in mice." (PMID 37335109, 2023).
lymphoma (4 papers, 2016 to 2022). A malignant (clonal) proliferation of B- lymphocytes or T- lymphocytes which involves the lymph nodes, bone marrow and/or extranodal sites. "WT and CD37KO lymphoma cells were treated with an inhibitor of the mitochondrial enzyme carnitine-palmitoyl-transferase 1a (CPT1a)." (PMID 36100608, 2022). "Furthermore, palmitate processing into energy was abolished in CD37KO lymphoma cells treated with CPT1a inhibitor in a concentration-dependent manner." (PMID 36100608, 2022). "Strikingly, inhibition of CPT1a with ST1326 resulted in significantly lower viability and proliferation of CD37KO lymphoma compared to WT lymphoma cells in a concentration-dependent manner." (PMID 36100608, 2022). "Similar to CPT1a inhibition, palmitate-induced energy production by CD37KO lymphoma cells was significantly diminished upon treatment with ACSL1 inhibitor compared to WT control cells." (PMID 36100608, 2022).
renal carcinoma (4 papers, 2017 to 2023). A carcinoma arising from the epithelium of the renal parenchyma or the renal pelvis. "The expression of CPT1A significantly inhibited cell proliferation in renal cancer cells and MDA-MB231 breast cancer cells, but activated cell proliferation in prostate cancer cells and in V600E melanoma." (PMID 37686221, 2023). "We used the plasmid transfection method to explore the biological role of CPT1A in renal cancer cells and performed CCK-8, wound healing, and Transwell invasion experiments." (PMID 33381539, 2020). "The results demonstrated that CPT1A can inhibit the proliferation, migration, and invasion of renal cancer cells." (PMID 33381539, 2020). "Moreover, consistently overexpressing CPT1A attenuated lipid accumulation in the clear renal cancer cells." (PMID 37686221, 2023). "Together, the observations make the case for new therapeutics in renal cancer that target various aspects of the characteristic changes in metabolism, including restoration of function of FBP1 and CPT1A." (PMID 29176561, 2017).
chronic lymphocytic leukemia (3 papers, 2024 to 2025). "RBMX regulates the mTOR signaling pathway by stabilizing CPT1A and participates in lipid metabolism and proliferation in chronic lymphocytic leukemia, promoting the progression of the disease." (PMID 40941025, 2025).
colorectal tumor (3 papers, 2022 to 2025). "Comprehensive metabolomic analyses identified extensive acylcarnitine accumulation following CPT1A upregulation by Coriobacteriaceae, which then activated the MAPK signalling pathway, ultimately causing progression of colorectal tumours." (PMID 38245554, 2024). "CPT1A has been shown to protect colorectal tumor cells from anoikis and supports BE and EAC spheroid growth, which is inhibited upon disruption of FAO." (PMID 36233047, 2022). "HFD has been shown to increase Coriobacteriaceae abundance, which may promote colorectal tumor development via the CPT1A–ERK signaling axis." (PMID 40732971, 2025).
esophageal squamous cell carcinoma (3 papers, 2023 to 2025). Esophageal squamous cell carcinoma (ESCC) is a type of esophageal carcinoma (EC) that can affect any part of the esophagus, but is usually located in the upper or middle third. "ETV4 transcription factor expression inhibits the expression of ubiquitin ligase RNF2, leading to increased expression of the key enzyme CPT1A involved in fatty acid oxidation, thereby playing a role in esophageal squamous cell carcinoma." (PMID 39944823, 2025). "CPT1A is significantly upregulated in esophageal squamous cell carcinoma (ESCC) cellines." (PMID 39944823, 2025). "For example, overexpression of CPT1A is related to poor clinical results for esophageal squamous cell carcinoma, while disruption of CPT1A may prevent tumor metastasis and anoikis resistance." (PMID 37965453, 2023).
Hypertension (3 papers, 2021 to 2023). The presence of chronic increased pressure in the systemic arterial system. "Interestingly, differential methylation at multiple genes (SLC7A11, PHGDH, TXNIP, LOC100132354, CPT1A, SLC1A5) is associated with both AC (this study) and with hypertension." (PMID 34857913, 2022).
liver disease (3 papers, 2023 to 2024). "The transcription factor PPAR is also a novel target for the treatment of liver disease and synergizes with PGC1α to promote CPT1A expression, which in turn increases fatty acid β‐oxidation; their cooperation plays a key role in fatty acid β‐oxidation." (PMID 39139977, 2024). "Liver-specific deletion of CPT1a promotes sexually dimorphic steatotic liver disease (SLD) in mice, and here we have identified new mechanisms by which females are protected from HFD-induced liver injury." (PMID 37797918, 2023). "We also wanted to analyze the effects of purified C. difficile-derived MVs on other key processes in the development of various liver diseases, such as the β-oxidation (CPT1A) and synthesis of fatty acid (FASN)." (PMID 37107193, 2023).
liver dysfunction (3 papers, 2018 to 2023). "Using a CPT1a liver-specific deficient mouse model, we show female mice depend on CPT1a for protection from the high-fat diet (HFD)-induced liver dysfunction." (PMID 37797918, 2023). "One patient with CPT1A deficiency was identified by recurrent hepatopathy, nephromegaly, rhabdomyolysis, and hemolytic anemia." (PMID 29519241, 2018). "Carnitine palmitoyltransferase 1A (CPT1A) deficiency is a long chain fatty acid oxidation disorder, typically presenting with hypoketotic hypoglycaemia and liver dysfunction during fasting and intercurrent illness." (PMID 35822099, 2022). "Male mice are more susceptible to HFD-induced liver dysfunction than female control mice, a condition that is not worsened by the absence of CPT1a." (PMID 37797918, 2023).
lymph node metastasis (3 papers, 2021 to 2024). "High pS63-c-Jun expression was correlated with advanced American Joint Committee on Cancer (AJCC) tumour node metastasis (TNM) stage and lymph node metastasis, and high CPT1A was also associated with lymph node metastasis." (PMID 37803002, 2023). "Carnitine palmitoyltransferase 1 A (CPT1A) as a key enzyme in fatty acid oxidation (FAO) whose deregulation has been reported to be associated with grade, pathological stage, lymph node metastasis and poor prognosis in patients with GC." (PMID 38802766, 2024). "Although, CPT1A expression was not proportional with tumour size or lymph node metastasis, high expression of CPT1A was negatively associated with overall survival (OS) of patients with thyroid cancer." (PMID 34976793, 2021).
metastatic disease (3 papers, 2020 to 2024). "Additionally, the combined 7.16.4 mAb treatment and Cpt1a deletion reduced the size and number of lung metastatic lesions, indicating the potential efficacy of this combination therapy in both primary and metastatic disease." (PMID 39097623, 2024). "CPT1A is upregulated in advanced metastatic tumors, suggesting that CPT1A may be a useful target for metastatic CRC treatment." (PMID 36755301, 2023).
multiple sclerosis (3 papers, 2019 to 2023). A progressive autoimmune disorder affecting the central nervous system resulting in demyelination. "Inuits have a low prevalence of multiple sclerosis, possibly associated with in CPT1A P479L mutation." (PMID 37033619, 2023). "Human mutations in carnitine palmitoyl transferase 1A (CPT1A) are correlated with a remarkably low prevalence of multiple sclerosis (MS) in Inuits (P479L) and Hutterites (G710E)." (PMID 31527712, 2019). "CPT1A inhibition may represent a prospective therapeutic therapy for multiple sclerosis." (PMID 37033619, 2023).
serous ovarian cancer (3 papers, 2020 to 2025). "In high-grade serous ovarian cancer, cisplatin-resistant cells exhibit elevated fatty acid uptake and CPT1A-mediated FAO, while CPT1A inhibition effectively restores chemosensitivity." (PMID 41350297, 2025).
ulcerative colitis (3 papers, 2024 to 2026). An inflammatory bowel disease involving the mucosal surface of the large intestine and rectum. "In ulcerative colitis mice, down-regulation of CPT1A inhibits PPARα signaling pathway." (PMID 39088466, 2024).
Abdominal obesity (2 papers, 2017 to 2022). Excessive fat around the stomach and abdomen. "Out of the WC pathways, five pathways contained the DMP annotated to gene CPT1A associated with WC and abdominal obesity." (PMID 28947923, 2017). "Recent studies demonstrated that the methylation of ABCG1, CPT1A, and SREBF1 genes was associated with some cardio-metabolic risk factors including total cholesterol and insulin levels, as well as anthropometric indices of general and abdominal obesity." (PMID 35551677, 2022).
asthma (2 papers, 2025 to 2026). "Notably, high concentration of n-3 LCPUFA upregulated CPT1A and ANGPTL4, key genes involved in the PPAR signaling pathway, underscoring potential molecular mechanisms by which n-3 LCPUFAs may influence asthma susceptibility." (PMID 41149648, 2025). "Using primary BECs and Beas-2b cells, CPT1A-FAO was demonstrated to maintain superior barrier stability, secondary to its influence on mitochondrial regulatory and anti-inflammatory effects on HDM or Th1/Th2 cytokine-activated cells, which is a critical link in the progression of asthma." (PMID 41555513, 2026).
autoimmune disease (2 papers, 2025). A disorder resulting from loss of function or tissue destruction of an organ or multiple organs, arising from humoral or cellular immune responses of the individual to their own tissue constituents. "An interesting study in mice, investigating the action of rapamycin in autoimmune diseases and its role in inhibiting Th17 cells by increasing Treg cells, showed that CPT1A was upregulated following administration of the drug." (PMID 40963613, 2025).
chronic kidney disease (2 papers, 2023 to 2024). Impairment of the renal function secondary to chronic kidney damage persisting for three or more months. "CPT1A is the rate-limiting enzyme for fatty acid metabolism, but deleting CPT1A in tubules has minimal effect on aging and chronic kidney disease." (PMID 38516886, 2024). "This is similar to the negative relationship seen in patients with chronic kidney disease, where decreased kidney CPT1A mRNA expression was linked with increased accumulation of short and middle chain acylcarnitines." (PMID 37275238, 2023).
depression (2 papers, 2017 to 2021). "This suggests an association between CPT1a upregulation and depression, as a consequence of upregulated lipid metabolism." (PMID 28526869, 2017). "Mitochondrial carnitine palmitoyl transferase 1a (CPT1a) is a key molecule involved in lipid metabolism and mutations in CPT1a causing reduced function is hypothesized to have a protective role in the development of depression." (PMID 28526869, 2017). "We found a significant upregulation of CPT1a mRNA levels in cerebellum of people with history of depression which committed suicide, compared to healthy controls." (PMID 28526869, 2017). "Moreover, CPT1a is found to be upregulated in suicide patients with history of depression." (PMID 28526869, 2017). "Therefore, we hypothesized that inhibition of CPT1a activity can be developed as an innovative treatment strategy for depression." (PMID 28526869, 2017). "The expression of CPT1a mRNA in pathological brain samples of patients that committed suicide with a history of depression and compared non-depressed controls that committed suicide was analyzed by affymetrix analysis." (PMID 28526869, 2017).